DDR2 (discoidin domain receptor tyrosine kinase 2)
Diseases named in the same sentence as DDR2 in open-access papers (continued):
Sharing a sentence is not in itself a finding about the gene and the disease.
fibrosarcoma (8 papers, 2013 to 2025). A malignant mesenchymal fibroblastic neoplasm affecting the soft tissue and bone. "Taken together, this study shows that activation of DDR1b and DDR2 in a 3D collagen matrix promotes growth of fibrosarcoma cells by activating differential pathways." (PMID 34957097, 2021). "However, collagen-mediated MT1-MMP expression in HT1080 fibrosarcoma cells was shown to be DDR2-independent, suggesting that the involvement of DDR2 is specific to fibroblasts." (PMID 39937000, 2025). "Given that DDR1b and DDR2 appear to have key roles in fibrosarcoma progression, drugs that target these RTKs may represent useful therapies." (PMID 34957097, 2021). "Moreover, DDR2, upon activation by 3D collagen, was able to target the cell cycle by increasing the expression of the cyclin-dependent kinase inhibitor p21CIP1 and thus inhibiting cell proliferation in a fibrosarcoma model." (PMID 32582700, 2020). "In fact, COL1 aging has been reported to impair discoidin domain receptor 2 (DDR2) activation and thus its cell growth suppressor effect in fibrosarcoma cells." (PMID 35004699, 2021). "Interestingly, DDR1b and DDR2, promoted tumor growth in the presence of collagen while DDR1b suppressed the lung metastasis of HT1080 fibrosarcoma cells in a xenograft model." (PMID 32492656, 2020). "Additionally, ectopic expression of DDR1b but not DDR2 suppressed experimental lung metastasis in this fibrosarcoma model." (PMID 34957097, 2021). "Although human fibroblasts express DDR2 but not DDR1, HT1080 human fibrosarcoma cells express both DDR1 and DDR2." (PMID 28270508, 2017).
osteoarthritis (8 papers, 2013 to 2024). A noninflammatory degenerative joint disease occurring chiefly in older persons, characterized by degeneration of the articular cartilage, hypertrophy of bone at the margins and changes in the synovial membrane. "Ddr1-/- mice were recently found to spontaneously develop osteoarthritis of the temporomandibular joint, suggesting that loss of Ddr1 and associated increases in Ddr2 may initiate MMP-13 upregulation, resulting in type 2-collagen degradation." (PMID 32330138, 2020). "A large number of studies have demonstrated the involvement of DDR2 in the disease process of rheumatoid arthritis and osteoarthritis." (PMID 38217541, 2024). "DDR2 expression increases in the cartilage of patients with osteoarthritis and correlates with the degree of cartilage damage in human knee joints." (PMID 34602056, 2021). "DDR2 expression has also been shown to be increased both in mouse models of osteoarthritis (OA) and in human OA." (PMID 28886342, 2017). "Consistent with previously discussed studies, DDR2 is shown to be a major effector of MMP-13 expression in DMM models, such that almost complete protection from osteoarthritis is shown in DDR2 hypomorphic strains." (PMID 27478294, 2016). "HtrA1, Ddr-2, and Mmp-13 are reliable biomarkers for osteoarthritis (OA), yet the exact mechanism for the upregulation of HtrA-1 is unknown." (PMID 23755017, 2013). "DDR1 and DDR2 bind to collagen also to exert biological functions, like embryo development, ECM remodeling, organ fibrosis and osteoarthritis." (PMID 37122820, 2023).
pulmonary fibrosis (8 papers, 2016 to 2025). Chronic progressive interstitial lung disorder characterized by the replacement of the lung tissue by connective tissue, leading to progressive dyspnea, respiratory failure, or right heart failure. "In this context, it is pertinent to note that DDR2 has previously been linked to pulmonary fibrosis in mice." (PMID 31805124, 2019). "Experimental studies employing animal models have demonstrated that the downregulation of DDR2 can mitigate the development of lung fibrosis." (PMID 39518365, 2024). "In the context of lung fibrosis, DDR2 synergistically interacts with TGF-β and fibrillar collagen to facilitate the conversion of Fibroblasts into myofibroblasts, as well as the upregulation of vascular endothelial growth factor." (PMID 39518365, 2024). "Studies have shown that mice with a DDR2 deletion had significantly reduced bleomycin-induced pulmonary fibrosis." (PMID 31169440, 2019). "Recently, we showed that myeloid-derived CD45+DDR2+ cells isolated from lung tissue of mice with pulmonary fibrosis expressed high levels of CD80 and MHC II and were capable of stimulating an inflammatory T cell cytokine response." (PMID 31015794, 2019). "Conversely, upregulation of DDR2 expression significantly increased bleomycin-induced pulmonary fibrosis in mice." (PMID 31169440, 2019). "Our previous work in a mouse model of silica-induced pulmonary fibrosis showed that a subset of myeloid-derived CD45+DDR2+ cells honed to lung tissue, expressed markers of immune activation, and were capable of skewing T cell cytokine production." (PMID 31015794, 2019). "Moreover recent studies advocated that abolition of DDR2 reduces lung fibrosis and angiotensin‐induced cardiac fibrosis." (PMID 40468620, 2025). "In order to assess the contribution of the CFP population to fibrotic lung, lung digest from silica- or saline-instilled animals was analyzed by flow cytometry for the presence of CFPs (CD45+DDR2+ cells) (saline control, silica-induced pulmonary fibrosis, fourth panels)." (PMID 28700752, 2017). "Previous studies suggest that abolition of DDR2 reduces lung fibrosis and angiotensin‐induced cardiac fibrosis by regulating the expression of collagen and vital cellular processes, which also indicate that DDR2 might as well be required for adventitial remodelling." (PMID 40468620, 2025). "Importantly, the immune subset of this population has not previously been described, nor have the contribution(s) of this novel DDR2-expressing population to pulmonary fibrosis ever before been investigated." (PMID 28700752, 2017). "Our studies have shown increased deposition of collagen with silica-induced pulmonary fibrosis, which is concurrent with the increased percentage of the CD11b+CD11c+ subset of CFPs expressing CD80/CD86, suggesting that DDR2/collagen I signaling may play a role in activation of the immune CFP subset." (PMID 28700752, 2017).
colorectal cancer (7 papers, 2021 to 2026). A primary or metastatic malignant neoplasm that affects the colon or rectum. "Decreased DDR2 in colorectal cancer showed reduced metastasis." (PMID 38304289, 2023). "However, DDR2 signalling in HSCs can protect against chronic liver fibrosis progression but not early-stage liver injury (prefibrotic stage) and can inhibit liver metastasis of colorectal cancer." (PMID 37007062, 2023). "Thus, the liver microenvironment produced by DDR2-/- HSC-derived myofibroblasts based on the stimulation of tumour tissue, rather than MMP2 released insufficiently by DDR2-/- HSCs, may be the major contributor to the development of liver metastases derived from colorectal cancer." (PMID 37007062, 2023). "Although there were several genes in this region related to colorectal cancer including BCL920 and DDR2,21, 22 we could not identify upregulated genes as a result of copy number gain in this region." (PMID 35343095, 2022).
squamous cell carcinoma (7 papers, 2013 to 2025). A carcinoma arising from squamous epithelial cells. "Dasatinib, a multi-targeted TKI used to treat chronic myeloma, was proven to be an effective treatment for DDR2-mutated squamous cell carcinoma of the lung in xenograft models." (PMID 27793038, 2016). "In a preclinical model the multikinase TKI dasatinib with activity against DDR2 showed activity in squamous carcinoma cell lines harboring DDR2 mutations." (PMID 26018876, 2015). "Furthermore, cancer genome sequencing efforts have identified a series of oncogenic DDR2 point mutations that occur at low frequency in lung SCC (squamous cell carcinoma)." (PMID 23822953, 2013). "Targeted proteomic profiling of a panel of lung SCC (squamous cell carcinoma) DDR2 mutants demonstrated that SHP-2 is tyrosine-phosphorylated by the L63V and G505S mutants." (PMID 23822953, 2013). "Squamous-cell carcinoma (SCC) is distinguished by somatic mutations in genes such as SOX2, platelet-derived growth factor receptor A (PDGFR-A), fibroblast growth factor receptor 1 (FGFR1), and discoidin domain receptor tyrosine kinase 2 (DDR2)." (PMID 40429689, 2025). "Finally, mutations in the discoidin domain receptor 2 (DDR2) gene, a receptor of tyrosine kinase, were found in 4% of squamous cell carcinomas." (PMID 36661704, 2023). "Especially, it significantly correlates with a poor prognosis of adenocarcinoma, but DDR2 expression does not considerably correlate with squamous cell carcinoma." (PMID 28754957, 2017).
colon carcinoma (6 papers, 2013 to 2024). "Loss of DDR2 has also been shown to predispose hepatic tissues to colon carcinoma cell growth and metastasis." (PMID 23822953, 2013). "While many studies have found DDR2 playing a prometastatic function, DDR2-null mice were found to have a 3-fold increase in colon cancer metastasis." (PMID 36713812, 2022). "Furthermore, the receptor tyrosine kinases discoidin domain receptors DDR1 and DDR2 are also involved in type 1 collagen-mediated invasion and metastasis of colon carcinoma." (PMID 36741692, 2022).
lung adenocarcinoma (6 papers, 2013 to 2025). A carcinoma that arises from the lung and is characterized by the presence of malignant glandular epithelial cells. "For instance, COL10A1 interacts with DDR2 to facilitate cancer cell proliferation and migration, enhancing the migration, invasion, and proliferation of lung adenocarcinoma." (PMID 40002743, 2025). "Several other driver molecular alterations have been identified in lung adenocarcinoma, including somatic mutations of KRAS, BRAF, STK11, DDR2 and members of the FGFR family, as well as ALK rearrangements." (PMID 24236184, 2013). "In lung adenocarcinoma, type X collagen enhances metastatic potential by promoting FAK phosphorylation through DDR2 activation." (PMID 40563472, 2025).
neuroblastoma (6 papers, 2013 to 2025). Neuroblastoma (NB) is the most common solid, extracranial childhood tumor. "Sitravatinib, a multi-kinase inhibitor with an affinity for DDR2 and other similar kinases, has shown effectiveness in preclinical models of high-risk neuroblastoma." (PMID 39459560, 2024). "High expression levels of collagen receptor kinase, Discoidin domain receptor II (DDR2), are associated with the poor survival of neuroblastoma patients." (PMID 39459560, 2024). "Hence, it can be hypothesized that the transcriptional axis MYCN/TWIST1/DDR2/SNAIL1 could drive high-risk neuroblastoma tumor invasion and metastasis." (PMID 34716856, 2022). "This is consistent with our findings that DDR2 is also required for proper neuroblastoma cell proliferation." (PMID 38538106, 2024). "The combined results obtained for control and DDR2-downregulated cells suggest that collagen activation of DDR2 tyrosine kinase is required for normal neuroblastoma growth and spreading." (PMID 39459560, 2024). "It is plausible that DDR2 modulates integrin-mediating mechanics to collagen substrates in this neuroblastoma cell line." (PMID 39459560, 2024). "In summary, these experiments suggest that DDR2-downregulated neuroblastoma cells exhibit altered mechanotransduction activity when plated on collagen-I cross-linked PAA gels." (PMID 39459560, 2024). "In summary, we provide the first study, to our knowledge, on the possible mechanical changes generated by the collagen-binding receptor, DDR2, in the neuroblastoma cell line, SH-SY5Y, for controlling the mesenchymal phenotype." (PMID 39459560, 2024). "To systematically examine the effects of DDR2 signaling and substrate stiffness on cancer cells, in the present study, we performed RNA‐seq analysis of a human neuroblastoma cell line SH‐SY5Y." (PMID 38538106, 2024). "As a non‐typical collagen receptor, DDR2 binds to fibrous collagen I. Dysregulated DDR2 expression has been documented in various cancer types including neuroblastoma." (PMID 38538106, 2024). "Our results provide insight into the mechanics of collagen-binding receptor DDR2 as a critical pathway for controlling aggressive neuroblastoma cells." (PMID 39459560, 2024). "In this work, we directly measured the effects of downregulating DDR2 expression on the 2D migration of neuroblastoma by tracking individual cells’ MSD, which has been utilized as a tool to gain insight on the migratory mode." (PMID 39459560, 2024). "In this study, we used a novel neuroblastoma cell line with normal and downregulated DDR2 levels to conduct a study on the cellular mechanics of DDR2 upon activation of collagen I. We employed various parameters to verify the robustness of our results." (PMID 39459560, 2024). "Taken together, our results indicate that downregulation of DDR2 in neuroblastoma cells decreases cell proliferation and induces senescence that is independent of substrate stiffness." (PMID 38538106, 2024). "We also show that DDR2 is a critical pathway to control aggressive behavior that forms in neuroblastoma and that facilitates tumor cell invasion." (PMID 39459560, 2024). "Neuroblastoma cell lines and tumors express relatively high levels of DDR2, which is significantly correlated to a worse patient survival probability." (PMID 39459560, 2024). "In the present study, we provide the first study, to our knowledge, utilizing shRNA technology on SH-SY5Y cells to elucidate the role of DDR2 in mediating neuroblastoma cell mechanics and migration." (PMID 39459560, 2024). "More importantly, RTKs that have remained poorly studied in the context of neuroblastoma pathogenesis, such as DDR2 and PDGFRA, are now revealed as very robust and potentially critical modulators of neuroblastoma." (PMID 34716856, 2022). "Together, these results highlight the important role that DDR2 has in reducing migration mechanics in neuroblastoma and suggest DDR2 may be a promising novel target for future therapies." (PMID 39459560, 2024).
neuroblastoma (continued). "We found that downregulating DDR2 was a critical regulator of neuroblastoma cell maintenance." (PMID 39459560, 2024). "Our results also shed light on the action of DDR2 in neuroblastoma cells, which may contribute to migration mechanics and cell–cell and cell–ECM interactions." (PMID 39459560, 2024). "However, how neuroblastoma cells respond to substrate stiffness, as well as the role of DDR2 in sensing substrate stiffness are still poorly understood." (PMID 38538106, 2024). "Similarly, the neuroblastoma cells with downregulated DDR2 exhibited significantly decreased cell stiffnesses, protrusion lengths, and, consequently, lower traction forces compared to the control neuroblastoma cells." (PMID 39459560, 2024). "Moreover, high co-expression of RET and DDR2 distinguishes neuroblastoma cell lines from virtually any other cancer cell line in the CCLE." (PMID 34716856, 2022). "However, the mechanisms by which DDR2 modulates neuroblastoma cell mechanics and cell migration are still unknown." (PMID 39459560, 2024). "However, the role DDR2 plays in the metastasis of neuroblastoma remains ill-defined." (PMID 39459560, 2024). "Finally, our analysis and literature review suggest that DDR2 may be an excellent therapeutic target in neuroblastoma, a feature that is currently being addressed in our lab." (PMID 34716856, 2022). "This study demonstrates that both knocking down the collagen receptor DDR2 and increasing ECM stiffness can reduce neuroblastoma cell proliferation." (PMID 38538106, 2024). "In further analyses on the R2 Genomics Platform, we found very significant correlations between DDR2 and TWIST1 expression in every single neuroblastoma patient dataset available." (PMID 34716856, 2022). "We further investigated DDR2 expression in the Cancer Cell Line Encyclopedia (CCLE) and observed that neuroblastoma cell lines ranked in the top 2nd position for highest average expression." (PMID 34716856, 2022). "ALK, FGFR1, RET, PDGFRA, DDR2, EGFR, and IGF1R were enriched in endosomes from two or more neuroblastoma cell lines, but there were profound differences among cell lines." (PMID 25884760, 2015). "Phosphopeptides from several RTK’s that are known for their oncogenic roles in other human tumors were identified in this neuroblastoma cell line, including IGF-1R/IR, FGFR1, FGFR2, Ret, and DDR2." (PMID 24349301, 2013). "Surprisingly, RNA sequencing results show that the DDR2 knockdown significantly enhances the expression tumor suppressor genes in neuroblastoma cells, while the ECM stiffness does not." (PMID 38538106, 2024). "Therefore, it is not surprising that DDR2 is also essential for neuroblastoma growth." (PMID 39459560, 2024).
pancreatic cancer (6 papers, 2021 to 2025). "We assessed mRNA levels of COL11A1 and its receptors (integrin α1β1 and DDR2) by RT-qPCR in the pancreatic cancer cell lines BxPC-3, Capan-1, Mia PaCa-2 and PANC-1." (PMID 33531986, 2021). "In addition to mediating cell adhesion to COL11A1, we and others have shown that COL11A1 promotes ovarian and pancreatic cancer cell survival and chemotherapy resistance through ITGα1β1 and DDR2 in vitro." (PMID 33668097, 2021). "We found that integrin α1β1 and DDR2 mediate COL11A1-induced p-Akts437 activation during pancreatic cancer development, suggesting that blocking integrin α1β1 or DDR2 to inhibit the functions of COL11A1 is specific but not exclusive." (PMID 33531986, 2021). "However, in present study, we found there was no synergistic effect between integrin α1 and DDR2 in regulating pancreatic cancer cell function." (PMID 33531986, 2021).
prostate carcinoma (6 papers, 2015 to 2021). A carcinoma that arises from epithelial cells of the prostate gland. "DDR2 has been shown to be a cancer-related gene associated with prostate cancer aggressiveness and progression, and its expression is upregulated in advanced benign prostate hyperplasia and prostate cancer compared to normal tissue." (PMID 33917302, 2021). "Increasing evidences have demonstrated that up-regulation of DDR2 is commonly observed in multiply tumor types including breast and prostate cancer." (PMID 26362312, 2015). "DDR2 have also been shown to exhibit aberrant expression patterns in several tumor types, including nasopharyngeal and prostate cancer." (PMID 26362312, 2015). "In prostate cancer, overexpression of DDR2 improved adhesion to collagen I." (PMID 33917302, 2021). "Located on chromosome 1q23.3, discoidin domain receptor 2 (DDR2) is a member of the receptor tyrosine kinase (RTK) family, and has been closely associated with the progression of various cancers, including breast and prostate cancer." (PMID 34065317, 2021). "It is evident that dysregulation of the DDR2-collagen-LOXL2 axis in early prostate cancer would therefore provide a potent and pro-tumorigenic microenvironment, capable of driving aggressive disease and that this axis can be targeted with therapeutic interventions." (PMID 31061140, 2019). "Collectively, the up-regulation of CAF-derived collagen and DDR2 during early prostate cancer may potentiate a pro-tumorigenic loop and drive disease progression." (PMID 31061140, 2019). "For example, AR, EGFR, DDR2 and MAP2K2 were connected with mtDNA genes in prostate cancer, and TMPRSS2, NF1, PIK3CA, BRCA1 and TOP1 were the top neighbors of mtDNA genes in multiple cancer types." (PMID 32024997, 2020).